APOE (apolipoprotein E)
Diseases named in the same sentence as APOE in open-access papers (continued):
Sharing a sentence is not in itself a finding about the gene and the disease.
Alzheimer disease (continued). "The APOE4 variant of APOE has been identified as a risk factor for Alzheimer’s disease and is associated with increased disease severity in NPC1 patients." (PMID 32731618, 2020). "Another earlier research also observed an increased concentration of serum copper ions in a special kind of AD (Alzheimer’s disease epsilon four apolipoprotein E allele carriers)." (PMID 33081348, 2020). "In excess of the association between the APOE locus and dementia, we observed a small, but significant association between Alzheimer’s disease PGS and dementia." (PMID 33143703, 2020). "Our proof-of-concept study focused on the APOE locus, a clinically relevant genomic region, allowing for the analysis of numerous SNVs and haplotypes that have been linked to Alzheimer’s disease and other age-related diseases." (PMID 33271988, 2020). "We summarize how diet and Alzheimer’s disease (AD) risk are altered by APOE genotype in both animal and human studies and identify gaps." (PMID 32587511, 2020). "The ε4 allele of apolipoprotein E gene (APOE) is a well‐known risk factor of late‐onset Alzheimer's disease." (PMID 32426945, 2020). "One of the primary genetic risk factors for Alzheimer’s disease (AD) is the presence of the Ɛ4 allele of apolipoprotein E (APOE)." (PMID 32005122, 2020). "In this study, we used single-nucleus RNA sequencing (snRNA-seq) of human tissue to characterize microglial responses to Alzheimer disease neuropathologic change as a function of APOE and TREM2 risk genotypes." (PMID 32840654, 2020). "The APOE gene is the main genetic risk factor for Alzheimer’s disease/demetia and, in addition, associated with dyslipidemias." (PMID 33400738, 2020). "Apolipoprotein E (ApoE) has become a primary focus of research after the discovery of its strong linkage to Alzheimer’s disease (AD), where the ApoE4 variant is the highest genetic risk factor for this disease." (PMID 31947546, 2020). "Mutations in apolipoprotein E4 (APOE4) are the main risk factor, with the lifetime risk for Alzheimer’s disease being more than 50% for APOE4 homozygotes and 20–30% for APOE3 and APOE4 heterozygotes." (PMID 32493457, 2020). "The apolipoprotein E (APOE) gene contains both the major common risk variant for late onset Alzheimer’s disease (AD), e4, and the major neuroprotective variant, e2." (PMID 32948752, 2020). "The risk for Alzheimer's disease increases when HSV1 is present in the brains of APOE-ε4 carriers (OR 2.71)." (PMID 33403161, 2020). "Accumulating evidence indicates that ApoE polymorphism affects multiple physiopathological pathways in coronary heart disease and Alzheimer’s disease (AD)." (PMID 32795354, 2020). "The primary genetic risk factor for late onset Alzheimer’s disease (LOAD) is the APOE4 allele of Apolipoprotein E (APOE) gene." (PMID 33375167, 2020). "An important consideration for diseases such as Alzheimer’s disease—which have a genetic locus like APOE/TOMM40 conferring much of the genetic risk to the disease—is to determine how the remaining variants in the genome contribute to the disease." (PMID 33143703, 2020). "As well as our examination of associations with APOE, we tested the cumulative effect of common Alzheimer’s disease-associated genetic variants on neuropathology, clinical status and cognition." (PMID 33376986, 2020). "Despite its multifactorial profile, the primary genetic risk factor for late onset Alzheimer’s disease (LOAD) is the Apolipoprotein E (APOE) gene." (PMID 33375167, 2020). "What are the associations between the Alzheimer disease risk allele apolipoprotein E (APOE) ε4 and attention across the life span of individuals with Down syndrome?" (PMID 32986108, 2020). "Numerous studies have attempted to elucidate the underlying mechanism for APOE ε4 influences on Alzheimer disease onset and progression." (PMID 32379048, 2020).
Alzheimer disease (continued). "Taken together, our results provide insight into how genetic risk for Alzheimer’s disease influences both the clinical and pathological features of dementia, increasing our understanding about the interplay between APOE genotype and other genetic risk factors." (PMID 33376986, 2020). "The risk of Alzheimer’s disease is also influenced by different variants within the APOE promoter when they are present in phase (in cis on the same chromosome) with the ε4 haplotype." (PMID 33271988, 2020). "Late onset Alzheimer’s disease is highly heritable with the most established genetic risk factor being variants of the APOE gene." (PMID 33376986, 2020). "In Alzheimer’s disease (AD), the three APOE variants (ε2, ε3, and ε4) have been consistently associated with disease risk, making it the strongest single-gene predictor at a population level in neuropsychiatry." (PMID 32423490, 2020). "Apolipoprotein E epsilon 4 allele (ApoE4) is the single most significant genetic risk factor for sporadic Alzheimer’s disease." (PMID 32957083, 2020). "One of the major genetic risk factors for Alzheimer’s disease is apolipoprotein E (APOE), of which reduced function is associated with sleep apnoea, the progression of sleep disturbances, cognitive performance and sleep deterioration." (PMID 33212927, 2020). "The APOE ε4 haplotype (rs429358C–rs7412C) is an established risk factor for late-onset Alzheimer’s disease (LOAD) and other age-related diseases." (PMID 33271988, 2020). "Further, there is also emerging data from the UK Biobank cohort, again, that the ApoE e4 genotype, associated with both delirium and dementia, particularly a 14-fold high risk of Alzheimer's disease confers a higher risk of infection." (PMID 33192744, 2020). "The apolipoprotein E (ApoE) transporter protein genotype is an identified genetic risk factor for Alzheimer's disease." (PMID 33014081, 2020). "For example, the APOE gene (variants of which are recognised to be important in dementia risk) has been shown to be differently methylated in Alzheimer’s disease (AD)." (PMID 32111184, 2020). "It is noteworthy that APOE ε4 is associated not only with Alzheimer disease but also with altered brain metabolism and structure in young cognitively normal adults." (PMID 32379048, 2020). "One copy of APOE-ε4 (inheriting a CC at these two locations from either parent) confers a threefold risk of Alzheimer’s disease while two copies (inheriting a CC at these two locations from both parents) a 15-fold increase in risk." (PMID 33143703, 2020). "Known risk factors for cognitive decline include older age, lower education, and genes such as apolipoprotein E (APOE) that plays an important role in the risk for Alzheimer’s disease." (PMID 33488674, 2020). "The family-based GWAS of the National Institute of Aging-Late Onset Alzheimer Disease Family Study (NIA-LOAD38) included association tests within APOE strata." (PMID 33090224, 2020). "APOE ε4 carriers not only have a higher risk but also an earlier onset of Alzheimer disease by 10 to 20 years in a gene dose-dependent manner." (PMID 32379048, 2020). "Of particular interest was the association of MHQ data availability with the apolipoprotein E (APOE) ε4 genotype that is a major risk factor for Alzheimer's disease." (PMID 31263887, 2020). "Apolipoprotein E (APOE) was the first discovered and is by far the strongest genetic risk factor for late-onset Alzheimer's disease (LOAD)." (PMID 32859588, 2020). "Astrocytes that carry the ε4 allele of apolipoprotein E (APOE), an allele associated with a higher risk of Alzheimer’s disease, have a reduced autophagic flux and impaired capacity to clear amyloid plaques in a mouse model of the disease." (PMID 32260050, 2020).
Alzheimer disease (continued). "There are critical gaps in our understanding of sex differences in Alzheimer’s disease (AD) including the higher prevalence of AD, the steeper cognitive decline, and a stronger effect of the apolipoprotein E ε4 allele (APOE4) on AD risk in women versus men." (PMID 32560743, 2020). "Liu CC, Kanekiyo T, Xu H, Bu G. Apolipoprotein E and Alzheimer disease: risk, mechanisms and therapy." (PMID 32876203, 2020). "The apolipoprotein E (ApoE) e4 genotype is associated with an increased risk of dementia and Alzheimer’s disease." (PMID 32983152, 2020). "Next, say we want to use our newly developed risk prediction model as a diagnostic tool for Alzheimer’s disease in another population B in which we know there is a different prevalence of the APOE ε4 allele." (PMID 32615926, 2020). "The rarity of Alzheimer’s disease in the UK Biobank sample also explains the limited association of APOE in the healthspan GWAS, compared to the other ageing traits." (PMID 32678081, 2020). "We removed genes flanking the APOE region (± 500 kb) due to its strong association with Alzheimer’s disease and identified 29 significant associations." (PMID 32299494, 2020). "Apolipoprotein E4 (ApoE4) is the most prevalent genetic risk factor for late-onset Alzheimer’s disease (AD)." (PMID 32630431, 2020). "The capillary type of CAA is associated with advanced stages of Alzheimer’s disease-related pathology, the presence of the apolipoprotein E (APOE) ε4 allele, and complement immune system activation." (PMID 32431603, 2020). "The minor allele of CLOCK gene polymorphism 3111T/C was associated with higher susceptibility of Alzheimer’s disease only in APOE ε4 carriers." (PMID 32913680, 2020). "The existence of APOE polymorphisms have a direct impact on the risk of developing late-onset Alzheimer disease (LOAD), with APOEε4 carriers having the greatest risk to develop AD." (PMID 32709045, 2020). "In support, correlation of herpes virus-1 (HSV-1) infection with Alzheimer disease increases for individuals with the APOE-e4 allele (lipoprotein precursor gene)." (PMID 31963711, 2020). "Apolipoprotein E (APOE), the major susceptibility gene for late-onset Alzheimer’s disease (AD), has three common alleles (APOE2, 3, and 4), giving rise to six genotypes (APOE2/2, 2/3, 3/3, 2/4, 3/4, and 4/4)." (PMID 32015339, 2020). "The ε4 allele of apolipoprotein E (APOE) gene and increasing age are two of the most important known risk factors for developing Alzheimer disease (AD)." (PMID 32817639, 2020). "We also investigated the association between the dosage of APOE ɛ4 risk allele, a major Alzheimer’s disease risk factor, and RBA." (PMID 32001736, 2020). "APOE-ε4 is a main genetic risk factor for developing late onset Alzheimer’s disease (LOAD) and is thought to interact adversely with other risk factors on the brain." (PMID 33188215, 2020). "The apoE 4 allele, which is a well-known risk factor for Alzheimer disease was a significant prognostic factor for improvements in memory test performance in non-verbal long-term memory." (PMID 32478173, 2020). "Recent studies have shown that APOE ε4 is not only a major risk factor for Alzheimer’s disease but also an independent risk factor for progression to severe cerebral amyloid angiopathy and cerebral amyloid angiopathy-related cerebral hemorrhage." (PMID 33328970, 2020). "Variation at the APOE genetic locus is an established risk factor for Alzheimer’s disease (AD), and cognitive decline in domains of memory, information processing speed and overall cognitive function (‘g’)." (PMID 30903549, 2020). "In recent years, several studies have shown that APOE polymorphism is associated with the efficacy of DNP in the treatment of Alzheimer's disease." (PMID 32636753, 2020). "Several studies have demonstrated that the APOE ε4 allele is an independent risk factor for Alzheimer’s dementia." (PMID 33328970, 2020).
Alzheimer disease (continued). "The ε4 allele of the apolipoprotein E (APOE) gene (APOE ε4) is the major genetic risk factor for Alzheimer disease." (PMID 32379048, 2020). "In the current study, the authors investigate how sex and APOE ε4 genotype modify the association between Alzheimer’s disease biomarkers and metabolites in serum." (PMID 32123170, 2020). "Apolipoprotein E (APOE) is an important risk factor for cognitive decline and Alzheimer’s disease in aging individuals." (PMID 33488674, 2020). "An unresolved question is to what extent this effect is dependent on the ApoE-ε4, a genotype associated with risk of Alzheimer’s Disease (AD)." (PMID 31760549, 2020). "Given the importance of the apolipoprotein E (APOE) gene for risk of Alzheimer disease, determining this genotype is important in cognitive aging studies." (PMID 31977056, 2020). "ApoE has three allelic isoforms (apoE2/E3/E4) of which apoE4 is strongly associated with Alzheimer’s disease." (PMID 33363547, 2020). "The apolipoprotein E ε4 allele (APOE*ε4) is indicated as a risk for Alzheimer's disease and other age-related diseases." (PMID 32381152, 2020). "The apolipoprotein E gene (APOE) is the strongest genetic risk factor for late-onset Alzheimer’s disease (AD), yet the expression of APOE is not clearly understood." (PMID 31978088, 2020). "A genetic predisposition to CRCI is the E4 allele of the Apolipoprotein E gene (APOE), which is also the strongest genetic risk factor for Alzheimer’s disease." (PMID 33352780, 2020). "The pretest probability was 50%, the APOE test results were high-risk (i.e. ε3/ε4 and ε4/ε4), and the probability of Alzheimer's disease was 79%." (PMID 33101544, 2020). "Genetic variation in the apolipoprotein E (APOE) gene is associated with Alzheimer's disease (AD) and risk factors for cardiovascular disease (CVD)." (PMID 32346601, 2020). "Prospective cohort studies that include persons irrespective of their cognitive stage or neuropathological diagnosis are needed to clarify the absolute lifetime risk of neuropathologically confirmed Alzheimer’s dementia for each APOE genotype." (PMID 32015339, 2020). "Apolipoprotein E (APOE) ε4 allele is a major genetic risk factor for Alzheimer disease and mild cognitive impairment (MCI)." (PMID 32379048, 2020). "Taken together, these results suggest that APOE status and Alzheimer’s disease PRS are independently associated with neuropathology, combining in an additive manner to influence an individual’s accumulation of tauopathy (NFTs) and β-amyloid plaques." (PMID 33376986, 2020). "The Apolipoprotein-E (APOE) ε4 gene allele, the highest known genetic risk factor for Alzheimer’s disease, has paradoxically been well preserved in the human population." (PMID 32528115, 2020). "Apolipoprotein E (APOE) ε4 allele is the strongest known genetic risk factor for Alzheimer disease (AD) in the general population." (PMID 32817639, 2020). "In the context of late-onset Alzheimer’s disease, with a minor allele frequency of 0.14, the ε4 allele of the APOE gene is the strongest common genetic risk factor in people with central European ancestry (odds ratio about 3.5)." (PMID 32226939, 2020). "Since the reported prevalence and impact of different APOE genotypes on Alzheimer’s dementia risk depends in part on age, race, ethnicity, geographic location, education, and dementia severity, these estimates are likely to vary in different populations." (PMID 32015339, 2020). "Associations between APOE ε4 alleles and memory impairment among people with Alzheimer’s disease have been previously noted." (PMID 30514930, 2020). "Women with APOE ε4 genotype are known to have an increased risk of Alzheimer’s disease (AD) compared with men with APOE ε4." (PMID 32903525, 2020). "We aimed to present an overview of the literature regarding the interaction between physical exercise and APOE gene polymorphism on cognitive function, particularly in patients with Alzheimer's disease (AD)." (PMID 33331535, 2020).
Alzheimer disease (continued). "The ε4 allele of apolipoprotein E (APOE) gene, the major genetic risk factor for Alzheimer’s disease (AD), has also an impact on hippocampal subfields." (PMID 32804326, 2020). "The apolipoprotein E (APOE) e4 allele is the most common genetic variant associated with Alzheimer’s disease (AD)." (PMID 32770103, 2020). "The apolipoprotein E (APOE) e4 allele is the most common genetic variant associated with Alzheimer’s disease (AD), with the presence of an allele increasing the risk of developing AD1–4." (PMID 32770103, 2020). "The apolipoprotein E (APOE) ε4 allele is the most critical genetic risk factor for Alzheimer’s disease (AD) and cognitive impairment." (PMID 32231559, 2020). "The apolipoprotein E (APOE) gene contains both the major common risk variant associated with clinically diagnosed late onset Alzheimer’s disease (AD), APOE e4, and a neuroprotective variant, APOE e2." (PMID 32948752, 2020). "The ε2 and ε4 alleles of the apolipoprotein E (APOE) gene are associated with Alzheimer disease (AD) risk." (PMID 33090224, 2020). "Is genetic variation near the apolipoprotein E gene (APOE) associated with risk of Alzheimer disease (AD) independently of the ε2/ε3/ε4 genotype?" (PMID 33090224, 2020). "Possession of the ε4 allele of apolipoprotein E (APOE) is the primary genetic risk factor for the sporadic form of Alzheimer’s disease (AD)." (PMID 33148345, 2020). "The inheritance of ε4 allele of apolipoprotein E (APOE) is the major genetic risk factor for late-onset Alzheimer’s disease (AD)." (PMID 32703241, 2020). "Carriers of the APOE e4 allele are at higher risk of age-related cognitive decline and Alzheimer’s disease (AD)." (PMID 32080211, 2020). "AD genotypes (such as the combinations of APOE variants) are commonly tested and linked to the risk for Alzheimer’s disease." (PMID 32225014, 2020). "The APOE ε4 allele (i.e. ApoE4) is the strongest genetic risk factor for sporadic Alzheimer’s disease (AD)." (PMID 33032659, 2020). "In humans, variants of the ApoE gene, i.e., the ApoE ε4 allele, increase the risk of developing Alzheimer’s disease (AD), possibly due to its association with cardiovascular disease." (PMID 32344633, 2020). "Genome–wide association studies (GWAS) have revealed a plethora of putative susceptibility genes for Alzheimer’s disease (AD), with the sole exception of APOE gene unequivocally validated in independent study." (PMID 32694537, 2020). "Advanced age and apolipoprotein E (APOE) ε4 allele are both associated with increased risk of the Alzheimer’s disease (AD)." (PMID 32572010, 2020). "The apolipoprotein E (APOE) ε4 gene has emerged as a major genetic risk factor for Alzheimer's disease (AD) 1-3." (PMID 32929366, 2020). "The strongest genetic risk factor for late-onset Alzheimer's disease (AD) is allele ε4 of the apolipoprotein E (ApoE) gene, which was discovered in 1993." (PMID 33343331, 2020). "It is well established that the ε4 allele of the apolipoprotein E gene (APOE4) is a strong risk factor for late-onset Alzheimer’s disease (AD) and that APOE2 is protective." (PMID 33074098, 2020). "The apolipoprotein E (APOE) genotype is closely associated with the risk of Alzheimer’s disease (AD), the most common form of dementia." (PMID 32054532, 2020). "The ε4 allele of APOE is the largest genetic risk factor known to date for late‐onset (sporadic) Alzheimer's disease (AD)." (PMID 32426945, 2020). "Apolipoprotein E (APOE) is a major genetic risk factor contributing to the development of late-onset Alzheimer’s disease (AD)." (PMID 32226373, 2019). "Apolipoprotein E (APOE) genotype is the strongest prevalent genetic risk factor for Alzheimer’s disease (AD)." (PMID 30958695, 2019). "Specifically, APOE has three isoforms, 2, 3, and 4: APOE2 is associated with elevated plasma LDL level and increased cardiovascular disease risk, whereas APOE4 is associated with increased risk of Alzheimer’s disease." (PMID 31034468, 2019).